VHL (von Hippel-Lindau tumor suppressor)
Diseases named in the same sentence as VHL in open-access papers (continued):
Sharing a sentence is not in itself a finding about the gene and the disease.
follicular carcinomas of the thyroid (2 papers, 2006 to 2014). "It therefore would be interesting to compare VHL expression in PTC with follicular adenoma (FA) and follicular thyroid carcinoma (FTC) in further investigations." (PMID 25490036, 2014).
Hepatic hemangioma (2 papers, 2016). A congenital vascular malformation in the liver composed of masses of blood vessels that are atypical or irregular in arrangement and size. "Loss-of-function mutations in the von Hippel-Lindau tumor suppressor gene (VHL) could lead to age-dependent hepatic hemangiomas in mice." (PMID 27872856, 2016). "Inactivation of HIF-2α can suppress the formation of hepatic hemangiomas in VHL mutant mice, suggesting that HIF-2α might promote the formation of hepatic hemangiomas." (PMID 27872856, 2016).
Hyperparathyroidism-jaw tumor syndrome (2 papers, 2017 to 2020). "First, we examined the ExAC cohort for variants previously reported as disease-causing in six genes associated with penetrant monogenic disorders (i.e., FHH, MEN1 and MEN2, hyperparathyroidism-jaw tumor syndrome, NF1, and VHL)." (PMID 29308445, 2017).
Hypoglycemia (2 papers, 2013). A decreased concentration of glucose in the blood. "Downregulating the GLUT2 and glucose-6-phosphatase (G-6-Pase) genes by VHL deletion impedes the appropriate release of glucose from the liver, which results in abnormal hepatic accumulation of glycogen and hypoglycemia in VHL-deficient mice." (PMID 23874892, 2013). "In the current study, we revealed that VHL deletion remarkably enhanced glucose uptake into hepatocytes and caused severe hypoglycemia, which resulted in the death of these mice." (PMID 23874892, 2013). "Our conditional VHL knockout (VHL-KO) mice, having VHL gene deletion induced by tamoxifen, developed severe hypoglycemia associated with disproportionately increased storage of PAS-positive substances in the liver and resulted in the death of these mice." (PMID 23874892, 2013). "Summarily, our results indicate that VHL loss in endocrine cells during embryogenesis leads to neonatal hypoglycemia and perinatal lethality." (PMID 23977255, 2013). "We propose that aberrant glucagon secretion may underlie hypoglycemia in mice with VHL loss in neonatal islets." (PMID 23977255, 2013). "With regard to glucose metabolism mediated by the HIF system, two studies have reported that VHL disruption in adult hepatocytes resulted in increased glycogen granules, lipid droplets, and premature death due to hypoglycemia within weeks." (PMID 23874892, 2013). "Two lines of evidence suggest that hypoglycemia is the cause and not the consequence of VHL-associated lethality." (PMID 23977255, 2013). "In apparent contradiction to our hypothesis identifying glucagon-producing cells as the culprit for hypoglycemia and postnatal lethality of islet-specific Vhlh mutant mice, transgenic mice with VHL inactivation specifically in α-cells survive to adulthood." (PMID 23977255, 2013). "Based on the previous reports and our data, we postulated that hepatic VHL deletion activated an IGF-IR pathway through an accelerated complex formation with RACK1 and contributed to severe hypoglycemia." (PMID 23874892, 2013). "In contrast, compared to buffer treated-VHL-KO control mice (day 3 vs. day 9 glucose levels, p = 0.040), IGF-IR antagonist administration resulted in attenuation of hypoglycemia after tamoxifen injection (day 3 vs. day 9, p = 0.121: N.S.)." (PMID 23874892, 2013). "In this study, we demonstrated that VHL-inactivated hepatocytes had enhanced IGF-IR protein expression concomitant with enhanced IGF-IR and RACK1 interactions and glucose uptake in the liver, which resulted in severe hypoglycemia." (PMID 23874892, 2013). "Although our recent study demonstrated that enhanced NO production in glomeruli prevented the kidney from endothelial cell-targeted nephropathy, the results here implied that upregulated NO production induced by VHL deletion did not contribute to hypoglycemia in VHL-KO mice." (PMID 23874892, 2013).
Infertility (2 papers, 2022). "This alternation might suggest a role of infertility in the prelude of ccRCC, particularly with a VHL gene mutation." (PMID 35448166, 2022). "The male mice model carrying VHL gene conditional knockout presents significant abnormalities in testis development paired with defects in spermatogenesis and infertility, indicating that pVHL exerts testis-specific roles." (PMID 35205757, 2022). "However, it is unclear what percentage of male VHL patients are afflicted with male factor infertility." (PMID 35448166, 2022). "In contrast with the VHL murine model, no infertility or defect of spermatogenesis are reported in humans except for mechanical obstruction of seminal ducts due to epididymal cysts." (PMID 35205757, 2022).
lymphoma (2 papers, 2015 to 2023). A malignant (clonal) proliferation of B- lymphocytes or T- lymphocytes which involves the lymph nodes, bone marrow and/or extranodal sites. "A VHL-based PROTAC EZH2 degrader was subsequently tested in lymphomas; it was demonstrated to be more efficient than CRBN ligand-based degraders in degrading EZH2, showed advantages over common inhibitors in inhibiting tumor growth in lymphoma xenografts in vivo, and had no obvious toxicity." (PMID 36770884, 2023).
malignant glioma (2 papers, 2017 to 2019). A grade III or grade IV glioma arising from the central nervous system. "Interestingly, one of the correlated regions was the promoter of ID2, a transcriptional regulator that supports a pro-survival role in malignant gliomas by inactivating VHL." (PMID 31806013, 2019).
Multiple renal cysts (2 papers, 2021 to 2024). The presence of many cysts in the kidney. "The overall risk of developing a potential VHL-related feature (haemangioblastoma, RCC or multiple renal cysts) was 17.3% at 10 years follow-up, and the risk of developing a potential VHL-related tumour (haemangioblastoma or RCC) was 10.8% at 10 years follow-up." (PMID 34573396, 2021).
osteoporosis (2 papers, 2019 to 2024). A condition of reduced bone mass, with decreased cortical thickness and a decrease in the number and size of the trabeculae of cancellous bone (but normal chemical composition), resulting in increased fracture incidence. "Our findings demonstrated the potential of VHL and C77 as guiding factors in the development of CKIP-1-based Proteolysis-Targeting Chimeras (PROTACs), which could be future therapeutic interventions in disuse osteoporosis." (PMID 39201556, 2024).
pancreatic adenocarcinoma (2 papers, 2023 to 2025). "The pancreatic adenocarcinoma is rare in VHL, as are endocrine or exocrine insufficiencies." (PMID 40918781, 2025).
polyposis (2 papers, 2016 to 2021).
preeclampsia (2 papers, 2022 to 2025). Preeclampsia is a hypertensive disorder of pregnancy that is characterized by new-onset hypertension with proteinuria presenting after 20 weeks of gestation, and depending on mild or severe forms may initially present with severe headache, visual disturbances, and hyperreflexia. "While VHL-related HIF abnormalities raise theoretical preeclampsia concerns, enhanced prenatal surveillance is unsupported." (PMID 41294695, 2025). "For example, VHL, a known regulator of HIF, is downregulated in the placentas of pregnancies complicated by preeclampsia and may also play an important role in the pathophysiology of the placentally-mediated complication of SPTB." (PMID 35462239, 2022).
spinal cord tumors (2 papers, 2022 to 2024). "Four of the RCC participants with germline VHL P/LP variants had clinical features characteristic of VHL disease (haemangioblastomas, multiple ccRCCs and spinal cord tumours)." (PMID 35441217, 2022).
tongue cancer (2 papers, 2012 to 2017). A malignant neoplasm affecting the tongue. "Patients with tongue cancer frequently show loss of heterozygosity (LOH) of the von Hippel–Lindau (VHL) tumor suppressor gene." (PMID 28549422, 2017). "However, the biological effect of VHL loss on tongue cancer remains unclear." (PMID 28549422, 2017). "In the present study, we noted no clear relationship between LOH of the VHL gene and the staining pattern of pVHL in tongue cancer." (PMID 28549422, 2017). "Recently, we observed frequent LOH of the VHL gene in sporadic tongue cancer but no somatic cell mutations such as missense, nonsense, and frameshift mutations." (PMID 22462637, 2012). "However, expression of VHL protein (pVHL) in tongue cancer has rarely been investigated and remains largely unknown." (PMID 28549422, 2017). "Regardless of LOH of the VHL gene, pVHL was expressed in cancerous and dysplastic tissue in all patients with tongue cancer." (PMID 28549422, 2017). "Immunohistochemical staining of pVHL in formalin-fixed, paraffin-embedded sections of cancerous and other tissues from 19 tongue cancer patients showed positivity for LOH of VHL in four samples, negativity in four samples, and was non-informative in 11 samples." (PMID 28549422, 2017).
type 1 diabetes mellitus (2 papers, 2023 to 2024). A chronic condition characterized by minimal or absent production of insulin by the pancreas. "To examine the effects of PT hypoxia reflected as VHL-mediated HIF-1α stabilization in conditions of type 1 diabetes mellitus, we generated mice with deletion of Vhl in the early PT S1/2 segments by cross-breeding Vhlflox mice, termed control (con), with Sglt2cre mice, termed VHL∆PT." (PMID 37626062, 2023).
adenovirus infection (1 paper, 2024). "To further investigate whether VHL affects inflammation in hepatocytes, we used VHL-overexpressing primary hepatocytes through adenovirus infection of mouse tail veins." (PMID 39585306, 2024).
age-related macular degeneration (1 paper, 2025). Age-related loss of vision in the central portion of the retina (macula), secondary to retinal degeneration. "The presence of glycolytic imbalance in a broad spectrum of neurodegenerative diseases, including age-related macular degeneration and glaucoma, highlights the clinical potential of targeting the VHL/HIF pathway." (PMID 39932789, 2025).
alveolar capillary dysplasia (1 paper, 2022).
autoinflammatory syndrome (1 paper, 2021). A group of disorders of the innate immune system characterized by attacks of seemingly unprovoked inflammation without significant levels of either autoantibodies or autoreactive T cells more characteristic of autoimmune disease. "For example, mutations in CYLD, USP8, A20 and the von Hippel-Lindau tumor suppressor (VHL; elongin-cullin-2-VHL (CRL2VHL) E3 ubiquitin ligase) are related to cylindromatosis, Cushing disease, autoinflammatory syndrome and heritable cancer syndrome, respectively." (PMID 33825941, 2021).
Azoospermia (1 paper, 2022). Absence of any measurable level of sperm,whereby spermatozoa cannot be observed even after centrifugation of the semen pellet. "The VHL, which is an autosomal dominant disorder, resulting from deletion or mutation in the VHL gene, has been linked to obstructive azoospermia." (PMID 35448166, 2022). "Here, we identified a heterozygous missense mutation in the VHL gene from a patient with azoospermia and multiple-organ cystic renal cell carcinoma." (PMID 35448166, 2022). "We report a xanthoderm with non-obstructive azoospermia (NOA)-associated cystic ccRCC, and the missense VHL mutation (c.262T > C, p.Try88Arg)." (PMID 35448166, 2022).
B-cell lymphoma (1 paper, 2023). "Among them, DT2216 has entered the clinical stage and with the best prospects, which targets B-cell lymphoma/leukemia-xL (Bcl-xL) to the VHL E3 ligase for degradation, thereby inhibiting the anti-apoptotic function of the B-cell lymphoma/leukemia-2 (Bcl-2) family." (PMID 38174069, 2023).
benign pheochromocytomas (1 paper, 2021). "According to one of the first studies from our research group on the miRNA expression profiles in FFPE samples of PPGL of various genetic backgrounds, miR-139-3p, miR-541 and miR-765 in VHL showed significantly higher expression compared to sporadic benign pheochromocytomas." (PMID 33810219, 2021).
Bloom syndrome (1 paper, 2022). Bloom syndrome (BSyn) is a rare chromosomal breakage syndrome characterized by a marked genetic instability associated with pre- and postnatal growth retardation, facial sun-sensitive telangiectatic erythema, increased susceptibility to infections, and predisposition to cancer. "BLM and VHL genes also contained germline mutations leading to Bloom syndrome and Von Hippel-Lindau (VHL) disease, respectively." (PMID 36451132, 2022).
calcific aortic valve disease (1 paper, 2021). "Aberrant expression of UBE2C leads to the degradation of pVHL (von Hippel-Lindau tumor suppressor), which increases HIF-1α levels, resulting in endothelial inflammation and epithelial-mesenchymal transition in calcific aortic valve disease." (PMID 34257576, 2021).
cardiomyopathy (1 paper, 2024). A disease of the heart muscle or myocardium proper. "To understand how chronic HIF activation promotes the development of cardiomyopathy, we inactivated the VHL gene in the mouse heart." (PMID 38881449, 2024).
carotid body paraganglioma (1 paper, 2021). A benign or malignant extra-adrenal parasympathetic paraganglioma arising from paraganglia adjacent to or in the bifurcation of the common carotid artery. "Out of the 24 patients, 9 (37.5%) carried pathogenic variants (2 SDHB, 7 NF1) and in one patient a novel VHL variant, classified as VUS was detected (VHL: p.36_37insSGPEE) in a young patient presenting with carotid body paraganglioma." (PMID 34439371, 2021). "A VUS VHL variant (NM_000551.4): c.123_137dupAGAGTCCGGCCCGGA (p.Ser43_Glu47dup) was identified in a patient with carotid body paraganglioma, which would have been missed or delayed significantly if the routine protocol had been applied." (PMID 34439371, 2021).
cavernous hemangioma (1 paper, 2016). A hemangioma characterized by the presence of cavernous vascular spaces. "Previous studies found that the signal pathway involving the von Hippel-Lindau (VHL) factor, the HIF-2α transcriptional factor, and HIF-2α target gene erythropoietin (EPO) could affect the formation of cavernous hemangiomas in mouse livers." (PMID 27872856, 2016).
Chordoid Meningioma (1 paper, 2020). A WHO grade II, usually recurring meningioma characterized by the predominance of tissues that are histologically similar to chordoma. "Together, the mutations in TRAF7, KLF4, AKT1, and VHL genes were mutually exclusive and occurred in 64.7% of the well-differentiated chordoid meningiomas from ED group #3." (PMID 31963394, 2020).
chromaffin tumors (1 paper, 2017). "Consensuses and guidelines suggest that metastatic and sporadic PHEOs/PGLs in VHL patients (as in patients with chromaffin tumors of yet unknown genotype) should be evaluated first with 18F-DOPA PET." (PMID 28890865, 2017).
chronic pyelonephritis (1 paper, 2014). "In the present study a single case of chronic pyelonephritis with end stage kidney from nephrectomy specimen of a 41 year old male patient which was processed as negative control for VHL surprisingly showed exon 3 VHL mutation." (PMID 25097537, 2014).
clear cell chondrosarcoma (1 paper, 2020). A rare, usually low grade chondrosarcoma characterized by the presence of tumor cells with clear cytoplasm. "Increased Cyclin D1 function leading to vascularized clear cell tumors may be a common molecular feature of VHL-associated tumors and clear cell chondrosarcoma, which could be useful for therapeutic purposes in the future." (PMID 31673890, 2020). "We describe a case of a VHL patient with a primary clear cell chondrosarcoma." (PMID 31673890, 2020).
CNS hemangioma (1 paper, 2023). "Four patients who tested positive for VHL had a history of CNS hemangioma." (PMID 37555194, 2023).
cutaneous T-cell lymphoma (1 paper, 2022). "Because VHL and CRBN expressions are extremely low in cutaneous T-cell lymphoma (CTCL) cells, the activity of VHL- and CRBN-based Bcl-xL PROTACs against CTCL were unfavorable." (PMID 35410300, 2022).
endothelial dysfunction (1 paper, 2024). In vascular diseases, endothelial dysfunction is a systemic pathological state of the endothelium (the inner lining of blood vessels) and can be broadly defined as an imbalance between vasodilating and vasoconstricting substances produced by (or acting on) the endothelium. "Here, disruption of the PHD2/VHL pathway and the role of HIF2α was investigated in a pseudohypoxia model of endothelial dysfunction simulating aspects of PAH and PH pathobiology." (PMID 39159362, 2024).
esophageal cancer (1 paper, 2025). A primary or metastatic malignant neoplasm involving the esophagus. "Combined VHL/HIF1A inactivation in breast and esophageal cancer cells can also provide resistance to ARV-771, a VHL-based bromodomain degrader that has anti-cancer activity." (PMID 41420106, 2025).
exocrine pancreas tumors (1 paper, 2023). "One group developed a VHL pNEN model through homozygous Cre-LoxP deletion of VHL using a glucagon promoter, showing islet dysmorphia and hyperplasia but mostly demonstrating exocrine pancreas tumors." (PMID 37568572, 2023).
facial angiofibroma (1 paper, 2021). "Moreover, these dermatological manifestations can either be localized lesions (e.g., facial angiofibroma in MEN1) or can be located on a widespread area of the skin (e.g., VHL)." (PMID 34692360, 2021).
Fanconi anemia (1 paper, 2025). Fanconi anemia (FA) is a hereditary DNA repair disorder characterized by progressive pancytopenia with bone marrow failure, variable congenital malformations and predisposition to develop hematological or solid tumors. "Six hub genes (FANCI, KAT2A, TACC3, TPX2, VHL, WSB1) were enriched in Fanconi anemia and HIF-1 pathways, affecting microtubules, spindle formation, and cytoskeleton dynamics during mitosis." (PMID 40832468, 2025).
gastric neuroendocrine neoplasm (1 paper, 2024). A neoplasm with neuroendocrine differentiation that arises from the stomach. "Herein, we present the case of a 23-year-old woman with VHL presenting with multiple gastric neuroendocrine neoplasms (gNENs) type 1 in the context of chronic autoimmune gastritis (CAG)." (PMID 38619811, 2024).
gastroenteropancreatic neuroendocrine tumors (1 paper, 2020). "Here, we aimed to analyze the role of metabolic players such as the amino acid transporter 1 (LAT-1) and glucose transporter 1 (GLUT-1), regulated by the oxygen-sensing mechanism Von Hippel Lindau-hypoxia-inducible factor (VHL-HIF), in gastroenteropancreatic neuroendocrine tumors (GEP-NET)." (PMID 33066332, 2020).
hamartoma (1 paper, 2023). A benign and excessive tumor-like growth of mature cells and normal tissues which grow in a disorganized pattern. "Hamartoma and neoplasm of the eye were associated with KRT1, VHL and SLC25A11." (PMID 37185447, 2023).
hepatitis C (1 paper, 2017). "For the first time, our present study has demonstrated that VHL expression is dramatically inhibited in human hepatitis C, alcoholic, and cholestatic cirrhotic livers compared with healthy liver samples and that this expression is concomitant with HIF-1α and HIF-2α accumulation." (PMID 28112200, 2017).